CTSG (cathepsin G)
Diseases named in the same sentence as CTSG in open-access papers (continued):
Sharing a sentence is not in itself a finding about the gene and the disease.
rheumatoid arthritis (8 papers, 2011 to 2024). A chronic, systemic autoimmune disorder characterized by inflammation in the synovial membranes and articular surfaces. "CTSG plays a role in the inflammatory response and it has been associated with different inflammatory diseases, especially some related to the bone such as rheumatoid arthritis, periodontitis, and bone metastasis." (PMID 31647805, 2019). "From the observations it was studied that three out of ten patients suffering from rheumatoid arthritis reported for restricted local deposits of cathepsin G and elastase." (PMID 35002435, 2022). "CTSG has been reported to play an important role in a variety of inflammatory diseases including rheumatoid arthritis, coronary artery diseases, and ischemic reperfusion injury, and also response to bone metastasis." (PMID 31647805, 2019). "The activity of CTSG in enhanced inside synovial fluids of patients with rheumatoid arthritis." (PMID 35002435, 2022). "CTSG serve its role in the pathogenesis of auto-immune disorder like rheumatoid arthritis." (PMID 35002435, 2022). "The publication titled “Cathepsin G and Its Role in Inflammation and Autoimmune Diseases” highlights the role of CTSG in inflammatory signaling pathways and its impact on cartilage deterioration in ailments such as rheumatoid arthritis (RA)." (PMID 39619085, 2024).
asthma (7 papers, 2011 to 2025). "It was characterized by the upregulation of genes related to neutrophils, such as OLFM4, which is produced by neutrophils and has been associated with asthma inflammation, and CTSG, the neutrophil protease cathepsin G, which has been involved in neutrophilic asthma." (PMID 35203504, 2022). "At the locus 14q11.2, the five genes: KIAA0323, SDR39U1, CMA1, CTSG and GZMH were located within a single 220 kb LD block surrounding the tag biomarker rs4982958 which was associated with asthma in this study." (PMID 22545103, 2012). "We identified a potential five-biomarker panel (BPIFA1, MUC5AC, CAMP, CTSG, and ANXA1) that illustrates the inflammatory activity of asthma in sputum and could improve asthma phenotyping, providing valuable insights into personalized treatment approaches." (PMID 38542471, 2024). "Moreover, compared to the group of severe asthma patients with airway obstruction and oral corticosteroid (OCS) use but no history of smoking, the Cathepsin G levels were significantly higher in this high BMI female group." (PMID 40110046, 2025).
chronic obstructive pulmonary disease (7 papers, 2012 to 2025). A chronic and progressive lung disorder characterized by the loss of elasticity of the bronchial tree and the air sacs, destruction of the air sacs wall, thickening of the bronchial wall, and mucous accumulation in the bronchial tree. "It acts as an inhibitor of neutrophil elastase, trypsin, chymotrypsin, thrombin, plasmin and cathepsin G. Deficiency of this protein mainly causes chronic obstructive pulmonary disease." (PMID 34199928, 2021). "PLTP expression is increased in chronic obstructive pulmonary disease through cleavage of PLTP by cathepsin G resulting in inflammation of the lung." (PMID 40822650, 2025). "Cathepsin G participates to a greater extent to inflammation and fibrosis establishment in chronic obstructive pulmonary disease (COPD) in humans." (PMID 33195599, 2020).
cystic fibrosis (7 papers, 2008 to 2025). Autosomal recessive disorder caused by pathogenic variants in the CFTR gene (cystic fibrosis transmembrane conductance regulator), which encodes a chloride and bicarbonate channel expressed in epithelial cells, and follow the diagnosis criteria. "The overexpression of cathepsin G and underexpression of SERPINB1 and SLPI have been reported in muco-obstructive respiratory diseases such as cystic fibrosis and COPD." (PMID 40650225, 2025).
emphysema (7 papers, 2011 to 2024). "The current model is limited to assessing only NE and PR3 footprints and does not evaluate the potential impact of cathepsin G, which has also been reported to contribute to elastin degradation, at least in a cigarette smoke-induced animal model of emphysema." (PMID 39015374, 2024). "Subsequent work has shown that other proteolytic enzymes contained in neutrophil granules such as proteinase 3 and cathepsin G also have the potential to induce many of the pathological changes observed in COPD, not just emphysema." (PMID 24229090, 2013).
periodontitis (7 papers, 2013 to 2025). An acute or chronic inflammatory process that affects the tissues that surround and support the teeth. "Other proteins that stand out are neutrophil defensin 1, annexin A1, lysozyme C, resistin, cathepsin G, myeloperoxidase, and azurocidin, which were upregulated between 2.8 and 25.1-fold in periodontitis." (PMID 40384977, 2025). "In another study, cathepsin G, cathelicidin antimicrobial peptide, protein S100-A7, 14-3-3 protein sigma and vitamin D-binding were found more frequently in chronic periodontitis when compared to healthy subjects." (PMID 24098404, 2013). "This work developed a new portable diagnostic biosensor that may detect periodontitis by using two common inflammatory salivary biomarkers, Human Neutrophil Elastase (HNE) and Cathepsin-G." (PMID 38637787, 2024). "The analysis of samples from patients with periodontitis and a healthy control demonstrated the capability of the multiplex biosensor to identify the existence of HNE and Cathepsin-G activity directly at the site." (PMID 38637787, 2024).
Arthritis (6 papers, 2011 to 2023). Inflammation of a joint. "It inhibits proteinase 3, neutrophil elastase, and cathepsin G. These serine proteases are released by joint invading neutrophils following inflammatory stimuli and have shown to be involved in arthritis development." (PMID 21345239, 2011). "Four proteases associated with arthritis, neutrophil-derived human elastase (HNE) and Cathepsin G (CG), fibroblast-derived matrix metalloproteinase 3 (MMP-3) and the serine protease dipeptidyl peptidase-IV (DPP-IV), were investigated for their ability to process HMGB1." (PMID 33391251, 2020). "Moreover, neutrophils from KO mice for both elastase and cathepsin G have impaired recruitment in a subcutaneous air-pouch model of inflammation, or arthritis induced by anti-collagen antibodies." (PMID 25211214, 2014).
colitis (6 papers, 2014 to 2024). Inflammation of the colon. "Inhibition of cathepsin D was followed by amelioration of mouse dextran sodium sulfate (DSS) colitis; the level of anti-cathepsin G antibodies was significantly higher in patients with severe colitis than in those with mild or moderate colitis (p < 0.05)." (PMID 39359476, 2024). "The physiological relevance of this high cathepsin G concentration can be questioned since we measured low cathepsin G activity in colon from control and colitis animals." (PMID 34639054, 2021). "Chymotrypsin-like, cathepsin G, elastase-like, and kallikrein activities were comparable in post-colitis and control animals." (PMID 34072320, 2021). "In our study, we observed a possible role for cathepsin G, which was increased in colitis animals, and PAR4, which modestly but significantly decreased after treatment with UAMC-00050." (PMID 34248633, 2021). "Although no direct evidence suggests that PAR4 is the target for cathepsin G in colitis, this study highlights the possibility of targeting cathepsin G or PAR4 as novel therapeutic approach." (PMID 24860547, 2014). "Interestingly, we also observed an upregulation of cathepsin G at the mRNA level in this colitis mouse model." (PMID 34248633, 2021). "The mRNA expression levels of the serine proteases cathepsin G, proteinase 3 and neutrophil elastase were upregulated, while matriptase and urokinase were downregulated and tryptase αβ1 and tryptase β2 were unaltered in colitis compared to control animals." (PMID 34248633, 2021).
colorectal cancer (6 papers, 2023 to 2026). A primary or metastatic malignant neoplasm that affects the colon or rectum. "It has been shown that Cathepsin G has a tumor-suppressive effect on colorectal cancer cells by controlling the activity of the Akt/mTOR/Bcl2-mediated anti-apoptotic signaling pathway." (PMID 39080685, 2024). "There have been reported that high expression of CTSG can inhibit the progression of colorectal cancer and oral squamous cell carcinoma." (PMID 38919521, 2024). "CTSG exerts anti-tumor effects in colorectal cancer by negatively regulating the Akt/mTOR/Bcl-2 signaling pathway, and its overexpression promotes apoptosis." (PMID 39839650, 2024). "To investigate CTSG's role in colorectal cancer, we compared gene expression of CTSG in normal and primary tumor tissues using TCGA." (PMID 37151875, 2023). "Interestingly, cathepsin G in NETs was reported to kill PIK3CA-mutant colorectal cancer cells after being internalized via cell surface protein RAGE." (PMID 41480760, 2026). "To reveal the details of how CTSG released during NETs formation kills cancer cells, we conducted a genome-wide CRISPR/Cas9 screening in colorectal cancer cell line DLD1 treated with neutrophil conditional medium containing CTSG." (PMID 41040318, 2025).
diabetes (6 papers, 2021 to 2025). "Cathepsin G (CTSG) and neutrophil elastase (ELANE), were both found to be secreted by neutrophils and play an important role in promoting inflammatory response and vascular endothelial cell permeability, which was closely related to the pathophysiology of diabetes." (PMID 40641746, 2025).
hepatocellular carcinoma (6 papers, 2023 to 2025). A malignant tumor that arises from hepatocytes. "IL-8 produced by liver cancer cells triggers the formation of NETs via an NADPH oxidase-dependent pathway, and NET-associated cathepsin G (cG) facilitates hepatocellular carcinoma metastasis both in vitro and in vivo." (PMID 38173719, 2023). "This phenomenon for NETs-associated Cathepsin G is also observed in hepatocellular carcinoma (HCC)." (PMID 38332915, 2023). "In the Transwell cell invasion assay, cathepsin G significantly promoted the invasive capacity of hepatocellular carcinoma (HCC) cells in vitro; the expression of cathepsin G in HCC tissues was closely associated with the long-term prognosis of patients." (PMID 41445740, 2025). "Additionally, cathepsin G, another serine protease abundant in NETs, has been reported to enhance the invasive capabilities of hepatocellular carcinoma cells." (PMID 40993312, 2025). "In in vitro studies on hepatocellular carcinoma (HCC), cathepsin G released during NET formation was shown to enhance cancer cell invasiveness by downregulating adhesion molecules and increasing the synthesis of proinflammatory mediators." (PMID 41303697, 2025). "In hepatocellular carcinoma, NET-derived cathepsin G (CTSG) promotes tumor cell invasion by regulating adhesion molecules and inflammatory mediators, a process that can be disrupted by DNAzyme I therapy, indicating its therapeutic potential." (PMID 39736788, 2024).
oral squamous cell carcinoma (6 papers, 2022 to 2024). "Zou et al7 reported that CTSG was associated with overall survival in patients with oral squamous cell carcinoma." (PMID 37089051, 2023). "Huang et al6 indicated that CTSG was a potential marker in oral squamous cell carcinoma." (PMID 37089051, 2023). "However, a recent study has demonstrated that CTSG was a prognostic biomarker for oral squamous cell carcinoma patients." (PMID 37588994, 2023). "Studies demonstrate the prognostic value of Cathepsin G in oral squamous cell carcinoma patients." (PMID 35725413, 2022). "CTSG was suggested as a prognostic biomarker in certain types of cancer including bladder cancer, LUAD, oral squamous cell carcinoma." (PMID 37143472, 2023).
Alzheimer disease (5 papers, 2019 to 2026). A progressive, neurodegenerative disease characterized by loss of function and death of nerve cells in several areas of the brain leading to loss of cognitive function such as memory and language. "This extended signature includes granule proteins CAMP, CTSG, DEFA3, and MPO secreted from neutrophils and points to olfactomedin 4 (OLFM4) as a new target for the prevention of Alzheimer's disease." (PMID 41316897, 2026). "The signature supports the role of APOE in lipid regulation through apolipoproteins and inflammation and includes, among others, neutrophil secreted granule proteins CAMP, CTSG, DEFA3, and MPO that point to inhibition of OLFM4 as a target for Alzheimer's disease therapeutics." (PMID 41316897, 2026).
autoimmune disease (5 papers, 2019 to 2024). A disorder resulting from loss of function or tissue destruction of an organ or multiple organs, arising from humoral or cellular immune responses of the individual to their own tissue constituents. "Cathepsin G is a well-known contributor to autoimmune disease but to our knowledge, this is the first report implicating it as a potential driver of NET formation." (PMID 38971315, 2024). "NETs are a network of histones, elastases, myeloperoxidase (MPO), and cathepsin G released by neutrophils, which can participate in the process of tumors, infections, autoimmune diseases, and other diseases." (PMID 36468006, 2022). "In agreement, the level of neutrophil α-defensin (HNP-1-3) was increased in blood of patients with T1D and SLE and in synovial fluid of RA and Cathepsin G, in several autoimmune diseases like dermatomyositis, scleroderma, systemic sclerosis, RA, SLE, Sjogren’s syndrome and T1D." (PMID 35058920, 2021).
bronchiectasis (5 papers, 2023 to 2025). Segmental, irreversible dilation of the bronchial tree resulting in the accumulation of secretions which leads to obstruction. "An imbalance between neutrophil-derived serine proteases (NSPs) (neutrophil elastase (NE), proteinase 3 (PR3) and cathepsin G (CatG)) and their inhibitors has been implicated in many chronic inflammatory respiratory diseases, including bronchiectasis." (PMID 37465817, 2023). "The excessive release of neutrophil serine proteases, such as neutrophil elastase, cathepsin G and proteinase 3, promotes a protease–antiprotease imbalance that correlates with increased inflammation in bronchiectasis and contributes to disease progression." (PMID 40174958, 2025). "In addition to NE, neutrophils secrete other NSPs, including cathepsin G (CatG) and proteinase 3 (PR3), which contribute to the pathophysiology of bronchiectasis by increasing inflammation further, leading to structural damage and promoting infection." (PMID 40753522, 2025).
glioblastoma (5 papers, 2016 to 2024). The most malignant astrocytic tumor (WHO grade IV). "Previous studies have shown that CTSG degraded MHC I on the human glioblastoma cell surface of primary immune cells." (PMID 33323544, 2020). "CTSG activity has been presented as a new way to glioblastoma treatment." (PMID 33323544, 2020). "For instance, Cathepsin G (CTSG) is an essential protease for modulating MHC I molecules levels in human glioblastoma cells, and upregulation of cathepsin G might facilitate the detection of cancer cells." (PMID 33224866, 2020).
Obesity (5 papers, 2022 to 2024). Accumulation of substantial excess body fat. "Many of the upregulated immature neutrophil genes (e.g., OLFM4, DEFA1, ELANE, CEACAM6, CEACAM8, CTSG) have been found to be differentially expressed in persons with obesity and type 2 diabetes, both common comorbidities with psychotic disorders." (PMID 37147304, 2023). "Because human SerpinA3 can also inhibit Cathepsin G, whether SerpinA3 can inhibit chronic adipose inflammation to ameliorate obesity and metabolic disorders by targeting Cathepsin G in humans merits further investigation." (PMID 37288300, 2023). "Furthermore, adipocyte-conditioned media obtained from patients with obesity increased (P<0.01) the release of IL-36γ and the expression (P<0.05) of cathepsin G (CTSG) in monocyte-derived macrophages." (PMID 35222417, 2022). "Therefore, in this study, the elevated expression of upregulated DEGs enriched in serine metabolism, such as ELANE, CTSG, and MMP8, could result in increased serine hydrolysis and a subsequent reduction in serine levels within the body, thereby contributing to the onset and development of obesity." (PMID 39609876, 2024).
Stroke (5 papers, 2013 to 2023). Sudden impairment of blood flow to a part of the brain due to occlusion or rupture of an artery to the brain. "Preclinical studies reported that NSPs (NE, CTSG, and PR3) augmented cerebral inflammation, enhanced vascular permeability, and caused tissue damage in experimental stroke models, which suggests that NSPs are reasonable intervention candidates in IS." (PMID 36906528, 2023). "Apart from MMP, other factors released after stroke, including reactive oxygen species(ROS), cathepsin G, proteases, myeloperoxidase, elastase, chemokines and cytokines, may also destroy neurovascular units, ultimately increasing the permeability of the BBB and the risk for HT." (PMID 32028265, 2020). "In addition to neutrophil-derived MMPs, other factors released from neutrophils after stroke, including ROS, myeloperoxidase, elastase, cathepsin G, proteinase 3, cytokines, and chemokines, can also disrupt the neurovascular unit and ultimately result in increased BBB permeability and HT." (PMID 27561990, 2016). "Hence, in clinical diagnosis and treatment, serum marker tests for A2M, LBP, CTSG, CST3, and FABP1 should be prioritized in patients with a high suspicion of stroke for early detection and timely intervention." (PMID 38090270, 2023).
ulcerative colitis (5 papers, 2014 to 2025). An inflammatory bowel disease involving the mucosal surface of the large intestine and rectum. "Reverse Mendelian randomization analyses suggested that ulcerative colitis (UC) might lead to elevated cathepsin G levels, while Crohn’s disease (CD) may cause a decrease in cathepsin B and L1 levels." (PMID 39359476, 2024). "Ulcerative colitis (UC) fecal supernatants, cathepsin G (Cat-G), and PAR-4 agonist can increase both paracellular permeability and myeloperoxidase activity." (PMID 24876677, 2014). "Cathepsin G and PAR4 are upregulated in ulcerative colitis patients, and inhibition of cathepsin G and PAR4, but not PAR1 or PAR2, is protective." (PMID 24860547, 2014).